VPS28 (VPS28 subunit of ESCRT-I)
Description:
Component of the ESCRT-I complex, a regulator of vesicular trafficking process.
Synonyms: CIIA
Tractability: Antibody: UniProt places it where antibodies can reach, with high confidence; its Gene Ontology location is reachable by antibodies, with high confidence. PROTAC: ubiquitination databases record sites on it; its protein half-life has been measured.
Gene: Protein-coding gene on chromosome 8 (144,423,601 to 144,429,499, reverse strand). Ensembl gene ENSG00000160948.
Subcellular location: Cell membrane; Late endosome membrane
Subcellular location (Human Protein Atlas): Vesicles; Cytosol
Pathways (Reactome):
Disease: Budding and maturation of HIV virion; HCMV Late Events; Membrane binding and targetting of GAG proteins
Autophagy: Late endosomal microautophagy
Vesicle-mediated transport: Endosomal Sorting Complex Required For Transport (ESCRT)
Gene Ontology:
Molecular function: protein binding; ubiquitin binding
Biological process: negative regulation of protein ubiquitination; positive regulation of protein catabolic process; positive regulation of ubiquitin-dependent endocytosis; ubiquitin-dependent protein catabolic process via the multivesicular body sorting pathway; macroautophagy; membrane fission; multivesicular body assembly; protein transport to vacuole involved in ubiquitin-dependent protein catabolic process via the multivesicular body sorting pathway; viral budding via host ESCRT complex; endosome transport via multivesicular body sorting pathway
Cellular component: cytoplasm; cytosol; early endosome; endosome; endosome membrane; ESCRT I complex; extracellular exosome; plasma membrane; late endosome membrane
Genetic constraint (gnomAD): Loss-of-function variants: 22 observed, 21.27 expected, observed/expected ratio (o/e) 1.03, 90% interval 0.74 to 1.48. The synonymous counts are far from expectation, so gnomAD's model fits this gene poorly and the ratio says little. Missense variants: 159 observed, 189.61 expected, observed/expected ratio (o/e) 0.84, 90% interval 0.74 to 0.96. Synonymous variants: 102 observed, 68.48 expected, observed/expected ratio (o/e) 1.49, 90% interval 1.27 to 1.75.
Homologues: Orthologues: mouse Vps28 (99% identical), guinea pig VPS28 (98% identical), pig VPS28 (98% identical), rat Vps28 (98% identical), dog VPS28 (98% identical), rabbit VPS28 (96% identical), tropical clawed frog vps28 (92% identical), macaque VPS28 (92% identical), zebrafish vps28 (87% identical), chimpanzee VPS28 (84% identical), Drosophila melanogaster Vps28 (59% identical), Caenorhabditis elegans vps-28 (43% identical).
Diseases named in the same sentence as VPS28 in open-access papers:
VPS28 is named in the same sentence as 13 diseases in open-access papers, as found by Europe PMC text mining. Sharing a sentence is not in itself a finding about the gene and the disease. The quoted sentences say what the papers report.
breast cancer (5 papers, 2020 to 2025). A primary or metastatic malignant neoplasm involving the breast. "VPS28 or miR-491-5p gain and loss of function experiments were performed to verify their potential effect on the biological functions of breast cancer cells." (PMID 34395516, 2021). "The elevated VPS28 expression was found in breast cancer tissues and was associated with a poor prognosis (p < 0.001)." (PMID 34395516, 2021). "Taken together, the in silico analyses outlined in this study highlight the role and function of VPS28 in breast cancer." (PMID 34395516, 2021). "Analysis of starBase data revealed that miR-491-5p levels expressed an inversely correlated trend with VPS28 levels in breast cancer cells." (PMID 34395516, 2021). "Bioinformatic analysis of databases such as TCGA, CPTAC, and CCLE highlighted the increased expression of VPS28 in breast cancer tissues and cell lines." (PMID 34395516, 2021). "Although our study only focused on the effect of VPS28 on the biological functions of breast cancer cells, our observations contribute to a better understanding of VPS28’s involvement in malignant tumorigenesis." (PMID 34395516, 2021). "The mRNA expression of VPS28 in breast cancer cell lines was tightly low than four types in total 39 cell lines (p = 9.7e-16)." (PMID 34395516, 2021). "In this study, public databases (including TCGA, CPTAC, and mirDIP) were searched to elucidate the role of VPS28 in breast cancer tissues and cells." (PMID 34395516, 2021). "To clarify the working mechanism of VPS28 in breast cancer cells, we used the mirDIP, starBase, and TargetScan tools to search for its upstream targets." (PMID 34395516, 2021). "Knockdown of VPS28 was shown to suppress the biological functions and enhance the apoptosis of breast cancer cell lines." (PMID 34395516, 2021). "More studies are required to fully understand the effect of VPS28 and miR-491-5p on breast cancer progression." (PMID 34395516, 2021). "Considering the regulatory effect of miR-491-5p on VPS28, we first transfected a VPS28-overexpressing plasmid into breast cancer cells." (PMID 34395516, 2021). "Micro RNA-491-5p, identified as a posttranscriptional regulator of VPS28, was downregulated in breast cancer tissues." (PMID 34395516, 2021). "By further tracking its upstream target, we identified miR-491-5p as a posttranscriptional regulator of VPS28 in breast cancer cell lines." (PMID 34395516, 2021). "In this study, we aimed to examine the role of VPS28 in breast cancer progression by measuring its effect on the proliferation, migration, invasion, and apoptosis of two breast cancer cell lines." (PMID 34395516, 2021). "Additionally, this study also found that the overexpression of VPS28 can counteract the suppressive effect of miR-491-5p overexpression on breast cancer progression." (PMID 34395516, 2021). "Thus, our in silico analysis demonstrates that miR-491-5p can suppress breast cancer progression by attenuating the expression of VPS28." (PMID 34395516, 2021). "The CCLE database showed that VPS28 was expressed in breast cancer cell lines." (PMID 34395516, 2021). "VPS28 expression pattern data in breast cancer tissues were collected using the Cancer Genome Atlas (TCGA) and Clinical Proteomic Tumor Analysis Consortium (CPTAC) databases and analyzed to assess the association of VPS28 with breast cancer prognosis." (PMID 34395516, 2021). "Furthermore, we also identified miR-491-5p as a posttranscriptional regulator of VPS28 in breast cancer cells." (PMID 34395516, 2021). "However, co-transfection of VPS28 and miR-491-5p counteracted the effect of the miR-491-5p mimic on breast cancer cell functions." (PMID 34395516, 2021). "However, less evidence is available regarding the involvement of VPS28 in breast cancer." (PMID 34395516, 2021).
breast cancer (continued). "Similar to the reported posttranslational downregulation of the ESCRT-1 binding partner VPS28 in siRNA-mediated TSG101 knockdown cell lines, we observed a concomitant upregulation of VPS28 in mammary tumors with high overexpression of TSG101." (PMID 40624726, 2025). "For example, MORF4L2, PKG1, VPS28, and KLHDC7B predict the survival time of patients, indicating that cancer domains also facilitate the identification of bio-markers for breast cancer." (PMID 38783355, 2024). "Analysis of MCF10A and human breast cancer cells (MDAMB231, BT474, MCF7, T47D, and MDAMB436) by qRT-PCR and Western blotting showed that T47D and MCF7 cells had the highest VPS28 expression levels compared with the other cell lines tested (*p < 0.05 and **p < 0.01)." (PMID 34395516, 2021). "Nevertheless, the relationships among VPS28, SMOC1, and breast cancer are not currently known, and thus, further investigation in BC patients is required." (PMID 32964046, 2020).
viral infection (4 papers, 2015 to 2025). "The cells were infected with HCoV-OC43, with N protein serving as an indicator of virus infection, and analyzed for the localization of the endogenous VPS28 and TSG101." (PMID 40407327, 2025). "Its interacting components are directly involved in endosomal sorting, which suggests that VPS28 could have function in virus infection." (PMID 26161868, 2015). "The protein levels of these ESCRT subunits (HRS, VPS28, VPS25, CHMP2B, CHMP4B, CHMP7, VPS4A and ALIX) in the VRC were significantly increased by the viral infection in a dose-dependent manner." (PMID 35120190, 2022).
colon cancer (1 paper, 2024). "Similarly as we reported for RKO colon cancer cells, depletion of TSG101 or VPS28 in HEK293 cells led to a strong intracellular accumulation of ubiquitin, likely due to the impairment of multiple ESCRT-I-mediated degradation processes." (PMID 39560723, 2024).
hepatoblastoma (1 paper, 2024). Hepatoblastoma (HB) is a malignant hepatic tumor and is the most common pediatric liver cancer. "To investigate whether reduced expression of the chosen genes occurred also in other cell types, we performed qRT-PCR analysis in HepG2 hepatoblastoma cell line with siRNA-mediated removal of TSG101 or VPS28 proteins using siTSG101#2 and siVPS28#1 or CRISPR-Cas9-mediated knock-out of TSG101 gene." (PMID 39560723, 2024).
invasive candidiasis (1 paper, 2019). "The deletion of Vps28 protein in C. albicans increases its susceptibility to echinocandins and azoles, and significantly reduces its virulence in a murine model of invasive candidiasis." (PMID 31835471, 2019).
cancer (7 papers, 2015 to 2026). A tumor composed of atypical neoplastic, often pleomorphic cells that invade other tissues. "The ESCRT-I complex, composed of Tumor Susceptibility Gene 101 (Tsg101), VPS37, VPS28 and Multivesicular body subunit 12 (Mvb12), serves as a pleiotropic regulator in cancer pathogenesis." (PMID 40746890, 2025). "Knockdown of TSG101, along with a second ESCRT-I protein, VPS28, enhanced uptake of anti-miR-21 across multiple cancer cell lines." (PMID 25550434, 2015). "Nevertheless, whether VPS28 regulates plasma membranes and cell apoptosis in the context of cancer remains unclear." (PMID 34395516, 2021). "Moreover, the expression of VPS28 varied among cancer subtypes, of which the Luminal subtype displayed the highest level of the VPS28 expression." (PMID 34395516, 2021). "Vacuolar protein sorting–associated protein 28 (VPS28), one of the four cytosolic proteins comprising the endosomal sorting complex required for the transport I (ESCRT-I) component, has been reported to be linked to various cancers." (PMID 34395516, 2021). "In our observation, inhibition of Tal due to the overexpression of TSGΔ154-1054 in cancer cells may add to the effect of VPS28 to effectively prevent TSG101 degradation." (PMID 26811492, 2016). "Since depletion of TSG101 and VPS28 resulted in restoration of uptake in SKHEP1 anti-miR-21 resistant clones, we asked if a similar effect could be achieved in additional cancer cells lines with inherently poor free uptake of oligonucleotides." (PMID 25550434, 2015).
infection (6 papers, 2013 to 2025). The state of being infected such as from the introduction of a foreign agent such as serum, vaccine, antigenic substance or organism. "Equine infectious anemia virus Gag protein association with Vps28 enhanced efficient release during infection." (PMID 37565750, 2023). "We thus analyzed the relocalization of endogenous VPS28 upon HCoV-OC43 infection." (PMID 40407327, 2025). "Importantly, we also found that Vps28 downregulated FMDV 3A protein during the authentic infection." (PMID 37565750, 2023). "TSG101, VPS28, MVB12A, and CHMP6 were knocked down individually in 293T cells, followed by infection of the cells with replication-competent HCoV-OC43." (PMID 40407327, 2025). "The results showed that Vps28 co-localized with VP0, VP1, and VP3 proteins, besides, we also determined that Vps28 co-localized with FMDV structural proteins during authentic infection, which confirmed the regulation of Vps28 on FMDV structural proteins." (PMID 37565750, 2023). "We then evaluated the effects of Vps28 on the FMDV RC, and the results showed that Vps28 significantly decreased the dsRNA levels in 3hours and 5hours post-infection." (PMID 37565750, 2023). "Taken together, these results, including the analysis of infections in VPS28 and TSG101 knockdowns, affirm the conclusion that the engagement of ALIX, but not the TSG101 or VPS28 (members of the ESCRT I complex), is required for the scission of LdLPVs." (PMID 40956840, 2025).
tumor (5 papers, 2014 to 2025). "By monitoring the proliferation, migration, and apoptosis of transfected cells, we found that VPS28 upregulation was involved in tumor progression by downregulating the miR-491-5p expression." (PMID 34395516, 2021). "In sheer contrast to these, a number of ESCRT-I, -II, -III mutations, such as those mapping to Tsg101, vps28, Vps25, vps20, when made homozygous in eye discs, display a Mutant Eye No Eclosion (MENE) phenotype that have been associated loss of tumor suppression in Drosophila." (PMID 24718108, 2014). "Compared with group B, we found that less RASGRP1, VPS28, and RAS downstream proteins p-MEK1/2 and p-ERK1/2 were expressed in mice tumor sections of group G. Moreover, the group G had high levels of ERBIN expression." (PMID 38773970, 2024). "The results showed that, regardless of the chip or protein levels, VPS28, HSF1, and PUF60 showed higher expression in tumour tissues than in normal tissues, while COL17A1 and SMOC1 showed significantly higher expression in the adjacent tissues compared with the tumour tissues." (PMID 32964046, 2020).
VPS28 also shares sentences with these, for which no sentence is quoted: bladder cancer (1 paper); Cognitive impairment (1); gastric adenocarcinoma (1); multiple myeloma (1); sarcoma (1).